LACRT (lacritin)
Description:
Modulates secretion by lacrimal acinar cells.
Tractability: Antibody: its Gene Ontology location is reachable by antibodies, with high confidence; UniProt places it where antibodies can reach, with medium confidence; UniProt predicts a signal peptide or a membrane-spanning region.
Gene: Protein-coding gene on chromosome 12 (54,630,811 to 54,634,895, reverse strand). Ensembl gene ENSG00000135413.
Subcellular location: Secreted
Gene Ontology:
Molecular function: collagen binding; growth factor activity; laminin-1 binding; protein binding
Biological process: calcineurin-NFAT signaling cascade; calcium-mediated signaling; defense response to bacterium; epithelial structure maintenance; negative regulation of apoptotic process; negative regulation of lipopolysaccharide-mediated signaling pathway; positive regulation of calcineurin-NFAT signaling cascade; positive regulation of calcium-mediated signaling; positive regulation of cell population proliferation; positive regulation of epithelial cell proliferation; positive regulation of epithelial cell proliferation involved in wound healing; positive regulation of macroautophagy; positive regulation of peptidyl-tyrosine phosphorylation; positive regulation of release of sequestered calcium ion into cytosol; positive regulation of secretion; protein localization to Golgi apparatus; tear secretion
Cellular component: extracellular region; secretory granule
Genetic constraint (gnomAD): Loss-of-function variants: 13 observed, 13.23 expected, observed/expected ratio (o/e) 0.98, 90% interval 0.64 to 1.55. The upper end of that interval is the gene's LOEUF score, 1.55, which puts it in group 6 of 6, group 1 being the genes least tolerant of losing a copy. Missense variants: 132 observed, 146.37 expected, observed/expected ratio (o/e) 0.9, 90% interval 0.78 to 1.04. Synonymous variants: 62 observed, 58.09 expected, observed/expected ratio (o/e) 1.07, 90% interval 0.87 to 1.32.
Homologues: Orthologues: chimpanzee LACRT (97% identical), macaque LACRT (88% identical). Paralogues in human: DCD (21% identical).
Diseases named in the same sentence as LACRT in open-access papers:
LACRT is named in the same sentence as 18 diseases in open-access papers, as found by Europe PMC text mining. Sharing a sentence is not in itself a finding about the gene and the disease. The quoted sentences say what the papers report.
dry eye (11 papers, 2013 to 2025). "Specifically, LACRT is secreted from the submandibular salivary gland and has been associated with inflammatory disorders such as dry eyes, while LCN‐1 is secreted from the lingual von Ebner's glands." (PMID 39895030, 2025). "Lacritin was found to be deficient in aqueous deficient dry eye (ADDE) and Sjögren’s syndrome (SS) DED." (PMID 33450870, 2021). "Stability suffers from lacritin downregulation in dry eye and would be further exacerbated by loss of OAHFA at the lipid/aqueous interface." (PMID 33187980, 2021). "N-94 and N-94/C-6 elevated the stored elastic modulus and diminished the loss modulus of both anti-C-term lacritin-depleted normal tears and dry eye tears." (PMID 33187980, 2021). "Because it protects against cells from stress, replacement of lacritin has been advocated as a form of treatment in dry eye." (PMID 26605353, 2014). "Their similarity to N- and C-termini of processed lipid stabilizing pulmonary surfactant protein B, together with lacritin's detection in broncheoalveolar lavage, and selective lacritin and C-terminal proteoform deficiency in dry eye were rationale for testing with tear lipids." (PMID 33187980, 2021). "We further report that C-terminal lacritin proteoforms are selectively deficient in dry eye." (PMID 33187980, 2021). "At all frequencies, normal tears (maximal loss factor 0.5) as well as N-94 or N-94/C-6 supplemented anti-C-term lacritin-depleted normal (respective maximal loss factors 0.2, 0.1) and supplemented dry eye tears (respective maximal loss factors 0.5, 0.6) are elastic." (PMID 33187980, 2021). "However, some studies have shown that lacritin monomers are selectively deficient in human dry eye, which leads to autophagic dysfunction in corneal epithelial cells during inflammation." (PMID 31950044, 2019). "Lacritin C-terminal synthetic peptide ‘N-94/C-6’ (‘Lacripep’) is equally active on aire−/− dry eye mice, and in initial humans studies [phase I/II trial (NCT03226444);]." (PMID 37034386, 2023). "It was shown that 0.05% CsA induced lacritin expression and lead to the improvement of signs and symptoms of dry eye in a chronic pseudo-immune rat model of dry eye." (PMID 33450870, 2021). "Tissue transglutaminase is elevated both in dry eye and in disrupted alveoli of premature infants with bronchopulmonary dysplasia and through cross-linking diminishes bioactive monomeric lacritin in place of inactive polymers." (PMID 33187980, 2021). "With N-94 or N-94/C-6 supplementation, these coalesce into two (anti-C-terminal lacritin-depleted) or one (dry eye) peaks." (PMID 33187980, 2021). "The initial maximal surface pressure as the instantaneous stress response differed substantially between normal (∼1.7 mN/m) and both anti-C-term lacritin-depleted normal (∼0.6 mN/m) and dry eye tears (∼0.6 mN/m;)." (PMID 33187980, 2021). "Lacritin has been shown to be decreased in conditions altering tear film such as blepharitis and dry eye, indicating the crucial role of this protein in infection and other conditions." (PMID 23308132, 2013). "Lacritin, a tear, plasma and CSF protein discovered out of an unbiased biochemical screen to address dry eye promotes basal tearing and restores homeostasis in dry eye mouse models." (PMID 37034386, 2023). "As per compression/expansion isocycling, spiking N-94 or N-94/C-6 into anti-C-term lacritin-depleted normal tears was fully corrective, but only partially so in dry eye tears in which the initial reading was elevated (respectively ∼1.2 and 1.6 mN/m) but then fell off precipitously with relaxation." (PMID 33187980, 2021). "Based on its function, the use of exogenous lacritin to stimulate autophagy could be a potential treatment approach for dry eye." (PMID 31950044, 2019). "Thus, the processed C-terminus of lacritin that is deficient or absent in dry eye tears appears to play a key role in preventing tear film collapse and as a natural slow release mechanism that restores epithelial homeostasis." (PMID 33187980, 2021).
dry eye (continued). "Lacritin dimers, trimers, and larger polymers are attributable to cross-linking by tear tissue transglutaminase, a calcium-dependent glutamine γ-glutamyltransferase that is active in normal tears and whose ocular surface expression is elevated in patients with Sjögren's syndrome dry eye." (PMID 33187980, 2021). "Thus, lacritin C-terminal proteoforms, but not apparently lacritin monomeric or polymeric forms, lower tear surface tension and when selectively absent or deficient in dry eye tears contribute to decreased film stability upon compression that can be largely rescued with N-94 or N-94/C-6." (PMID 33187980, 2021). "Lacritin, an eye-specific protein with anti-microbial, cytoprotective and wound-healing properties, predominantly secreted by lacrimal glands, is absent in conditions such as Dry eye and Keratitis." (PMID 26670139, 2015).
breast carcinoma (3 papers, 2014 to 2023). "Amplification of LACRT gene was reported to be associated with invasion of breast tumors and was suggested as a marker for circulating breast cancer cells which indicates connection of LACRT to metastatic behavior of breast tumors." (PMID 37620794, 2023). "LACRT expression has also been detected in breast tissue (normal breast tissue, breast cancer tissue and breast cancer cell lines)." (PMID 27158822, 2016). "Copy number amplification of LACRT was observed in breast cancer." (PMID 24884718, 2014). "Moreover, our results indicate potential regulation of DSC1 by NF-κB inhibitor parthenolide as we identified parthenolide to reduce DSC1 protein levels in MCF7 breast cancer cells as well as expression of IGFBP5, LACRT genes and proliferative pathway." (PMID 37620794, 2023).
keratitis (2 papers, 2013 to 2015). A corneal disease that is characterized by inflammation of the cornea. "Interestingly expression variation of lacritin and lipocalin isoforms in keratitis tears was also confirmed by western analysis." (PMID 23308132, 2013).
Alzheimer disease (1 paper, 2023). A progressive, neurodegenerative disease characterized by loss of function and death of nerve cells in several areas of the brain leading to loss of cognitive function such as memory and language. "A combination of four tear proteins—lipocalin 1, dermcidin, lysozyme C, and lacritin—was shown to have 81% sensitivity and 77% specificity for Alzheimer’s disease." (PMID 36983883, 2023). "Furthermore, the tear fluid of Alzheimer’s disease patients included considerably lower amounts of lysozyme, lipocalin 1, and lacritin, as well as higher levels of dermcidin." (PMID 36983883, 2023).
corneal degeneration (1 paper, 2017). "It has also been described that loss of corneal epithelial sulfate leads to corneal degeneration, and the health of the ocular surface involves soluble factors whose action may be strongly influenced by HPSE, as in the case of lacritin." (PMID 29379222, 2017).
corneal infection (1 paper, 2015). A viral or bacterial infectious process affecting the cornea. "In the present study, we demonstrate that lacritin plays a ‘saviour’ role during LPS-induced corneal infection." (PMID 26670139, 2015).
diabetic retinopathy (1 paper, 2021). "Regarding the inflammatory process, in tears, lactotransferrin, lipocalin 1 (LCN-1), lysozyme C, lipophilin A, lacritin, and immunoglobulin lambda chain levels increased in patients with diabetic retinopathy." (PMID 34575451, 2021).
fungal infection (1 paper, 2013). "Interestingly 2D western analysis reveals lipocalin and lacritin isoforms are at a negligible level in the early stage of fungal infection, but their level increase marginally during intermediate stage." (PMID 23308132, 2013). "Ten fold reduction in the level of lacritin in the infected group compared to control may have relevance to resistance to fungal infection." (PMID 23308132, 2013).
fungal keratitis (1 paper, 2013). "Quantitation of lacritin levels showed that this protein is down regulated significantly in fungal keratitis when compared to bacterial keratitis tears (data not shown)." (PMID 23308132, 2013).
viral infections (1 paper, 2023). "For the first time, we have identified new CRS-related genes such as ADGRG7, probably reflecting cellular-adhesion elements, LACRT, IBSP, MEPE, and IFITM5, probable antimicrobial genes with a potential role in viral infections." (PMID 36982612, 2023).
bacterial infection (2 papers, 2015 to 2023). "Thereby, it is assumed that natural LACRT is enzymatically cleaved into various proteoforms during specific environmental conditions (e.g., bacterial infection) eliciting its prosecretory and mitogenic biofunctions." (PMID 36677706, 2023). "This study is the first to highlight the protective role of lacritin and mechanism of its action during bacterial infection of cornea in vitro." (PMID 26670139, 2015).
infection (2 papers, 2013 to 2015). The state of being infected such as from the introduction of a foreign agent such as serum, vaccine, antigenic substance or organism. "Expression of proteins related to host immune response such as cystatin SA III potential precursor, lacrimal lipocalin precursor, lacritin precursor is reduced in infection." (PMID 23308132, 2013). "In view of the biological significance of lacritin in human eye, we investigated its role in human corneal epithelial (HCE) cells during lipopolysaccharide (LPS)-induced infection." (PMID 26670139, 2015). "Western blot analysis confirmed that lacritin protein was totally absent in early stage of infection." (PMID 23308132, 2013).
LACRT also shares sentences with these, for which no sentence is quoted: age-related macular degeneration (1 paper); blepharitis (1); breast tumors (1); macular edema (1); ovarian carcinoma (1); Sjögren's syndrome (1).